MFSD2B (MFSD2 lysolipid transporter B, sphingolipid)
Description:
Lipid transporter that specifically mediates export of sphingosine-1-phosphate in red blood cells and platelets. Sphingosine-1-phosphate is a signaling sphingolipid and its export from red blood cells into in the plasma is required for red blood cell morphology (By similarity). Sphingosine-1-phosphate export from platelets is required for platelet aggregation and thrombus formation (By similarity). Mediates the export of different sphingosine-1-phosphate (S1P) species, including S1P(d18:0) (sphinganine 1-phosphate), S1P (d18:1) (sphing-4-enine 1-phosphate) and S1P (d18:2) (sphinga-4E,14Z-dienine-1-phosphate) (Probable). Release of sphingosine-1-phosphate is facilitated by a proton gradient (By similarity). In contrast, cations, such as sodium, are not required to drive sphingosine-1-phosphate transport (Probable). In addition to export, also able to mediate S1P import (By similarity). Does not transport lysophosphatidylcholine (LPC) (Probable).
Synonyms: SLC59A2
Tractability: Antibody: UniProt places it where antibodies can reach, with high confidence; its Gene Ontology location is reachable by antibodies, with high confidence; UniProt predicts a signal peptide or a membrane-spanning region.
Gene: Protein-coding gene on chromosome 2 (24,010,081 to 24,063,321, forward strand). Ensembl gene ENSG00000205639.
Subcellular location: Cell membrane
Pathways (Reactome):
Metabolism: Sphingolipid de novo biosynthesis
Gene Ontology:
Molecular function: sphingolipid transporter activity; symporter activity
Biological process: lipid transport; positive regulation of platelet aggregation; sphingolipid biosynthetic process; sphingosine-1-phosphate receptor signaling pathway; transmembrane transport; carbohydrate transport; lipid translocation
Cellular component: plasma membrane; membrane
Genetic constraint (gnomAD): Loss-of-function variants: 56 observed, 53.69 expected, observed/expected ratio (o/e) 1.04, 90% interval 0.84 to 1.3. The upper end of that interval is the gene's LOEUF score, 1.3, which puts it in group 5 of 6, group 1 being the genes least tolerant of losing a copy. Missense variants: 645 observed, 639.68 expected, observed/expected ratio (o/e) 1.01, 90% interval 0.94 to 1.08. Synonymous variants: 287 observed, 279.62 expected, observed/expected ratio (o/e) 1.03, 90% interval 0.93 to 1.13.
Homologues: Orthologues: chimpanzee MFSD2B (99% identical), macaque MFSD2B (96% identical), pig MFSD2B (84% identical), rat Mfsd2b (82% identical), mouse Mfsd2b (82% identical), dog MFSD2B (81% identical), dog MFSD2B (79% identical), guinea pig MFSD2B (60% identical), tropical clawed frog mfsd2b (50% identical), zebrafish mfsd2b (49% identical), Caenorhabditis elegans mfsd-12 (14% identical). Paralogues in human: MFSD2A (41% identical), MFSD12 (19% identical).
Diseases named in the same sentence as MFSD2B in open-access papers:
MFSD2B is named in the same sentence as 20 diseases in open-access papers, as found by Europe PMC text mining. Sharing a sentence is not in itself a finding about the gene and the disease. The quoted sentences say what the papers report.
carotid arterial thrombosis (1 paper, 2021). "Similar results were also observed in a model for carotid arterial thrombosis Together, our results indicate that loss of Mfsd2b causes defects in the intrinsic functions of platelets, which suppresses their thrombotic properties." (PMID 33863882, 2021).
diabetes (1 paper, 2023). "Proof of concept is provided by the resistance of mice lacking the S1P exporter MFSD2B to diabetes-induced HbA1c elevation and thiobarbituric acid reactive substances (TBARS) generation in diabetic RBC." (PMID 38097610, 2023).
heart failure (1 paper, 2024). Inability of the heart to pump blood at an adequate rate to meet tissue metabolic requirements. "Pharmacologic inhibition of Mfsd2b may thus offer a novel approach to heart failure." (PMID 39110173, 2024).
Hyperglycemia (1 paper, 2023). An increased concentration of glucose in the blood. "Most importantly, we have demonstrated that high S1P (as in Mfsd2b deficient mice) completely prevented HbA1C elevation in hyperglycemia, clearly suggesting a protective role of S1P against RBC glucose overload." (PMID 38097610, 2023). "However, they dramatically differed in HbA1c concentrations: while Mfsd2b+/+ mice developed a 9-fold increase in HbA1c, Mfsd2b–/– mice were completely resistant to the HbA1c increase despite similar hyperglycemia." (PMID 38097610, 2023).
Sepsis (1 paper, 2023). Sepsis is defined as life-threatening organ dysfunction caused by a dysregulated host response to infection. "Thrombin has been considered as a potential therapeutic target for sepsis, and studying the thrombotic effects of Mfsd2b and S1P on platelets may be helpful for the treatment of the pathological process of sepsis in the future." (PMID 37746079, 2023).
thrombosis (1 paper, 2021). "Intriguingly, we show that whole-body Mfsd2b KO mice and Mfsd2b-specific deletion in platelets exhibit reduced venous thrombosis, whereas Mfsd2b expression in erythrocytes is dispensable for this process." (PMID 33863882, 2021). "We found that global Mfsd2b KO mice show significantly reduced venous thrombosis with reduced size and weight of thrombi." (PMID 33863882, 2021). "Together, our data show that lack of Mfsd2b prevents platelets from inducing venous thrombosis." (PMID 33863882, 2021).
thrombotic disorders (1 paper, 2021). "Our data support a mechanism in which inhibition of Mfsd2b causes lipotoxicity in platelets and this pathway may represent a novel strategy to reduce the functions of platelets in thrombotic disorders." (PMID 33863882, 2021).
cancer (4 papers, 2019 to 2021). A tumor composed of atypical neoplastic, often pleomorphic cells that invade other tissues. "The Sphingosine-1-Phosphate Transporter (SP1) gene MFSD2B, a regulator of self-renewal and differentiation in neural and cancer progenitor cells, was also differentially methylated at multiple CpG sites (n = 6)." (PMID 32046773, 2020). "Up to now, there is no direct data for the recently discovered Mfsd2b in cancer." (PMID 31330821, 2019).
MFSD2B also shares sentences with these, for which no sentence is quoted: COVID-19 (1 paper); deafness (1); gram-negative bacterial infections (1); human papillomavirus infection (1); Hypertension (1); infarct (1); infection (1); lung carcinoma (1); myocardial infarction (1); non-small cell lung carcinoma (1); schizophrenia (1); tumor (1).